FOXC1 (forkhead box C1)
Diseases named in the same sentence as FOXC1 in open-access papers (continued):
Sharing a sentence is not in itself a finding about the gene and the disease.
cancer (continued). "Especially, FOXC1 and LINC00511 were expressed at a higher level in ER− cancers." (PMID 34783649, 2021). "FOXC1 could increase gefitinib resitance in NSCLC, by which mechanism is related to the regulation of cancer stem cell properties." (PMID 34334155, 2021). "FOXC1 and FOXC2, some FOX subfamilies, appear to play a new role in cancer progression." (PMID 35178357, 2021). "Consequently, activated FOXC1 transactivates CXC chemokine receptor 1 (CXCR1), a crucial promoter of cancer cell motility through activation of Rho-GTPases, that increases invasion and metastasis in HCC." (PMID 34540690, 2021). "Furthermore, expression of miR-133 has been frequently linked to reduced cell proliferation and diminished invasive ability of cancer cells via downregulation of EGFR, FOXC1, FOXQ1 and PSEN114, 22-24." (PMID 34335946, 2021). "Importantly, we reveal a novel drug-resistance mechanism in which the transcription factor FOXC1 binds to the miR-31 promoter to increase the expression of miR31-5p and regulate LATS2 expression, resulting in cancer cell resistance to OXA." (PMID 31623173, 2019). "Together, these results demonstrate that FOXC1 may be a key transcription factor that regulates CD147 and the immune response systems in cancer cells." (PMID 29560120, 2018). "Moreover, FOXC1 knockdown decreased expression of Oct4, NANOG, SOX2 and ABCG2, which are important downstream target genes of beta-catenin in regulating cancer stemness." (PMID 30189871, 2018). "Recently, FOXC1 has been shown to activate GLI2 in a SMO independent SHH pathway, which partly explains the aggressiveness of BLBC cell and adds a new role for FOXC1 in cancer cell stemness." (PMID 29487724, 2018). "FOXC1 knockout followed by RNA-seq revealed that FOXC1 positively regulates many of the same genes that are overexpressed in SP cells, some of which (e.g., ABCB1 and ID3) have been shown to play a role in drug resistance and cancer stemness in previous reports." (PMID 35406487, 2022). "In support of FOXC1 playing a role in cancer progression, another meta-analysis reported that FOXC1 is 23.8% more likely to be expressed in late-stage cancers as opposed to early-stage cancers." (PMID 34540690, 2021). "Finally, the potential significance of post-translational regulation of FOXC1 in cancer must not be overlooked." (PMID 30764547, 2019). "Our study supports a critical role of CD147 regulated by FOXC1 in immune responses through suppression of immune response-activating signal transduction, and targeting CD147 could be a promising strategy for the treatment of cancer." (PMID 29560120, 2018). "In addition, the enrichment of FOXC1 and BLBC in BRCA1-mutant tumors may also be explained by development of cancer in FOXC1-expressing luminal progenitor cells, which are enriched in the setting of BRCA1 mutation." (PMID 27708239, 2016). "In conclusion, our study demonstrated, under baseline conditions and without any system-altering methodology, the regulation of FOXC1 and CD147 in the immune response system in a panel of 1,036 cancer cell lines." (PMID 29560120, 2018). "However, the function of FOXC1 in ESCC remains poorly studied, with no reports on its regulation of cancer stem cells in this context." (PMID 38413558, 2024). "Additionally, western blot and RT-qPCR analysis confirmed the positive regulation of CBX7 and IGF-1R on cancer stem cell markers CD133 and CD44, rescuing the negative influence of FOXC1 knockdown on these markers." (PMID 38413558, 2024). "The results of chromatin immunoprecipitation experiments showed that both EZH2 and OGT are targeted to the promoter regions of FOXA1 and FOXC1 and knockdown of EZH2 or OGT affects expression of studied genes in breast non-malignant (MCF10A) and cancer cells (MCF7, T47D and MDA-MB-231)." (PMID 29864144, 2018).
cancer (continued). "Although there are no direct FOXC1 inhibitors described to date, previous reports have indicated that FOXC1 is regulated by the phosphatidylinositol 3-kinase (PI3K)-AKT signaling, a pathway that is being aggressively targeted with multiple therapeutics across cancer types." (PMID 35406487, 2022).
infection (4 papers, 2016 to 2023). The state of being infected such as from the introduction of a foreign agent such as serum, vaccine, antigenic substance or organism. "Although studies of FOX genes in infection and kidney disease are scarce, current evidence suggests that FOXC1 activates inflammation under hypoxia, which may have a regulatory role in SARS-CoV-2 infection and renal dysfunction." (PMID 37026010, 2023). "The BMP5 shRNA infection is capable of reverse FoxC1-induced SGC fate." (PMID 30894517, 2019). "The differential methylation of genes involved in memory T-cell responses, such as CD44, FOXO1 and FOXC1, might contribute to the inability of the host to mount responses capable of clearing infection." (PMID 27484700, 2016).
Heart Disease (2 papers, 2017 to 2021). "Forkhead box C1 (FOXC1) is a transcription factor that has a role in cell growth and survival and also in heart diseases." (PMID 33922912, 2021).
psychiatric disorder (2 papers, 2022 to 2023). A disorder characterized by behavioral and/or psychological abnormalities, often accompanied by physical symptoms. "We have found GATA2, FOXC1 and TFAP2A among highly expressed TFs that are associated with DEGs are shared between PD and psychiatric disorders." (PMID 37654790, 2023).
adenocarcinoma (1 paper, 2022). A common cancer characterized by the presence of malignant glandular cells. "FOXC1 protein was present in 84% of serous ovarian cystadenomas and 66.7% of borderline cystadenomas, whereas its expression was observed in only 37.5% of adenocarcinomas, which suggests that FOXC1 is a better prognosis marker." (PMID 35884426, 2022).
retinopathy (1 paper, 2024). "Furthermore, FOXC1 regulates physiological revascularization and BRB formation in a model of retinopathy." (PMID 38755144, 2024).
skeletal dysplasia (1 paper, 2021). Any Mendelian diseases that affects growth and development of the skeleton. "Loss of both Foxc1 and Foxc2 caused a general skeletal dysplasia predominantly affecting the vertebral column." (PMID 34331943, 2021). "Loss of Foxc1 and Foxc2 function in Col2-cre–expressing cells results in skeletal dysplasia and disrupts skeletal mineralization." (PMID 34331943, 2021).
FOXC1 also shares sentences with these, for which no sentence is quoted: idiopathic pulmonary fibrosis (3 papers); primary open-angle glaucoma (3); Anophthalmia (2); Axenfeld anomaly (2); cerebellar malformation (2); ductal adenocarcinomas (2); Ductal carcinoma in situ (2); Hypertension (2); kidney disease (2); Microcornea (2); neurodegenerative disease (2); pancreatic adenocarcinoma (2); Peters anomaly (2); psoriasis (2); Rieger anomaly (2); Sepsis (2); acute lymphoblastic leukemia (1); adenoid cystic carcinoma (1); alopecia (1); anterior segment dysgenesis (1); atrial fibrillation (1); atrial septal defect (1); autosomal dominant disease (1); bacterial infection (1); Bamforth-Lazarus syndrome (1); benign ovarian tumors (1); Bladder Tumors (1); Blepharophimosis (1); blepharospasm (1); Bosch-Boonstra-Schaaf optic atrophy syndrome (1).
A further 79 diseases each share a sentence with FOXC1 in 1 paper.